HOMER1 (homer scaffold protein 1)
Diseases named in the same sentence as HOMER1 in open-access papers (continued):
Sharing a sentence is not in itself a finding about the gene and the disease.
central nervous system diseases (1 paper, 2024). "Homer scaffolding protein 1 (Homer1) is a postsynaptic scaffolding protein that exerts anti-inflammatory effects in most central nervous system diseases." (PMID 38091015, 2024).
colon (1 paper, 2023). "The newly identified miR nov-miR-590-5p may be involved in HOMER1 deregulation in CRC, particularly in right colon tumors, where a negative correlation was identified between this gene and the new miR." (PMID 37987361, 2023).
HOMER1 also shares sentences with these, for which no sentence is quoted: Cerebral ischemia (2 papers); Hyperglycemia (2); Hypertension (2); Intellectual disability (2); memory impairment (2); neurodegenerative disease (2); Obesity (2); alcohol (1); alcohol addiction (1); Arthritis (1); autism spectrum disorder (1); babesiasis (1); cardiomyopathy (1); diabetic cardiomyopathy (1); essential tremor (1); fragile X syndrome (1); hematoma (1); homocysteinemia (1); injury (1); intrahepatic cholangiocarcinoma (1); liver cancer (1); maturity-onset diabetes (1); neuropathy (1); peripheral nerve injury (1); triple-negative breast carcinoma (1); West syndrome (1); ZIKV infection (1).